FREM1 (FRAS1 related extracellular matrix 1)
Diseases named in the same sentence as FREM1 in open-access papers (continued):
Sharing a sentence is not in itself a finding about the gene and the disease.
renal agenesis (3 papers, 2010 to 2025). Renal agenesis (RA) is a form of renal tract malformation characterized by the complete absence of development of one or both kidneys (unilateral RA or bilateral RA respectively), accompanied by absent ureter(s). "It is possible that a similar mechanism underlies the development of renal agenesis in FREM1-deficient mice." (PMID 23536828, 2013). "Slit3-null mice also have unilateral and bilateral renal agenesis that is similar to that seen in FREM1-deficient mice." (PMID 23536828, 2013). "Further studies will be needed to determine the molecular mechanism by which decreased SLIT3 expression causes renal agenesis in Slit3-null mice and modulates the prevalence of renal agenesis caused by FREM1 deficiency." (PMID 23536828, 2013). "Phenotypic similarities–CDH and renal agenesis–also exist between FREM1-deficient mice and mice with recessive mutations in Slit3, which encodes an extracellular matrix protein." (PMID 23536828, 2013). "We found that Frem1 and Gata4 interact genetically in the development of lung lobulation defects and that Frem1 and Slit3 interact genetically in the development of renal agenesis." (PMID 23536828, 2013). "This suggests that Frem1 and Slit3 interact genetically in the development of renal agenesis and that Slit3 expression can modulate the penetrance of this FREM1-related phenotype in mice." (PMID 23536828, 2013). "These experiments reveal that Frem1 interacts genetically with Gata4 in the development of lung lobulation defects and with Slit3 in the development of renal agenesis." (PMID 23536828, 2013).
anorectal malformation (2 papers, 2023 to 2025). "FREM1 is widely expressed in some neural crest mesenchyme, it can be found in many syndromes such as Bifid Nose Renal Agenesis and Anorectal malformations (BNAR) and Manitoba-oculo-tricho-anal (MOTA)." (PMID 38097983, 2023).
breast tumor (2 papers, 2020 to 2025). "This approach identified six high-confidence candidate genes, among which ​​FREM1​​ emerged as the most consistently ​​downregulated gene in breast tumor tissues compared to matched normal samples​​." (PMID 41324818, 2025). "Moreover, the patients with elderly age, advanced clinical stage and distant metastases exhibited dramatically lower expression of FREM1, heralding the possibility of becoming a more aggressive phenotype for breast tumors with aberrant reduced FREM1 expression." (PMID 33058542, 2020).
heart failure (2 papers, 2020 to 2025). Inability of the heart to pump blood at an adequate rate to meet tissue metabolic requirements. "Similar to MNS1, there is limited research on FREM1-specific functions in heart failure, but it is hypothesized to play roles in tissue remodeling and repair processes after myocardial injury." (PMID 40297163, 2025). "Ultimately, a total of four genes (FCN3, FREM1, MNS1, and SMOC2) exhibited significant co-expression in individuals suffering from heart failure." (PMID 40297163, 2025). "Using existing gene expression data in the Gene Expression Omnibus (GEO) database, we screened differentially expressed genes (DEGs) of heart failure and identified six key genes (HMOX2, SERPINA3, LCN6, CSDC2, FREM1, and ZMAT1) by random forest classifier." (PMID 33401250, 2020). "Of these genes, CSDC2, FREM1, and ZMAT1 have never been associated with heart failure." (PMID 33401250, 2020).
HIV-1 infection (2 papers, 2021 to 2024). The type species of lentivirus and the etiologic agent of acquired immunodeficiency syndrome (AIDS). "The association of its minor allele with resistance to HIV-1 infection may be due to its influence in alternative splicing of FREM1, and/or it may be a marker for polymorphisms in the coding region that affects the structure and function of FREM1." (PMID 34360591, 2021). "Our subsequent studies showed that FREM1 mRNA is highly expressed in tissues that are relevant to vaginal HIV-1 infection." (PMID 34360591, 2021). "Subsequent studies showed that FREM1 mRNA is highly expressed in tissues relevant to mucosal HIV-1 infection, including cervical epithelial tissues, and TILRR is a major modulator of many genes in the NF-κB signal transduction pathway." (PMID 34360591, 2021). "FREM1 and TILRR in cervical epithelial tissues may play a potential role in vaginal HIV-1 infection." (PMID 34360591, 2021).
microphthalmia (2 papers, 2013 to 2023). Congenital or developmental anomaly in which the eyeballs are abnormally small. "There are few studies related to eyelid coloboma, with reports of candidate genes focusing on FREM1, which is associated with the phenotypes of anophthalmia, microphthalmia, and upper eyelid coloboma." (PMID 38066959, 2023).
congenital heart disease (1 paper, 2025). A heart disease that is present at birth. "Multisystem involvement was evident in patients with FREM1 or BBS4 variants (e.g., P12, P13, P25), presenting with bifid nose, skeletal anomalies, obesity, polydactyly, or congenital heart disease (CHD)." (PMID 41288877, 2025).
diaphragmatic hernia (1 paper, 2013). A congenital or acquired weakness or opening in the diaphragm which allows abdominal contents to protrude into the chest cavity; congenital diaphragmatic hernias are caused when the embryonic diaphragm fails to fuse. "Gata4+/Δex2 mice, which harbor a deletion in exon 2 of Gata4, have anterior congenital diaphragmatic hernias that are similar to those seen in FREM1-deficient mice." (PMID 23536828, 2013).
infiltrating ductal carcinoma (1 paper, 2020). "As for histological types, the FREM1 expression was dramatically higher in infiltrating lobular carcinoma (ILC) than that in infiltrating ductal carcinoma (IDC; p = 0.002)." (PMID 33058542, 2020).
inherited kidney diseases (1 paper, 2025). "The central positioning of COL4A family genes and FREM1 within the network further highlights their potential cooperative role in the pathogenesis of inherited kidney diseases (IKDs) in this cohort." (PMID 41288877, 2025).
invasive lobular breast carcinoma (1 paper, 2020). An infiltrating lobular adenocarcinoma of the breast. "The results demonstrated that FREM1 had a dramatically reduced expression in BC tissues, possessed an inverse correlation with stage, age, and metastasis, and exhibited a higher level in invasive lobular breast carcinoma than in ductal one." (PMID 33058542, 2020).
male breast carcinoma (1 paper, 2025). A malignant neoplasm involving the male breast. "The potential relevance of the BMS and FREM1 in male breast cancer (MBC) worth further investigation." (PMID 41324818, 2025).
metastatic tumor (1 paper, 2016). "Expression levels of miR-200a, miR-200b, miR-429, miR-30a-5p, miR-30a-3p, miR-30e, miR-30e-3p, CDH1, SLC22A24, C3orf52 and FREM1 were significantly decreased in metastatic (TNM stage III with pN+ and IV) compared to non-metastatic tumor (TNM stage I and II)." (PMID 27549611, 2016).
Metopic synostosis (1 paper, 2018). Premature fusion of the metopic suture. "A small proportion of metopic synostosis is caused by 9p22 deletions and point mutations in FREM1." (PMID 29845577, 2018).
Nephropathy (1 paper, 2016). A nonspecific term referring to disease or damage of the kidneys. "Of these, Frem1, Foxo1, and Setd7 have been implicated in the pathogenesis of nephropathy." (PMID 27736906, 2016).
Rectal prolapse (1 paper, 2013). Protrusion of the rectal mucous membrane through the anus. "This suggests that reduced anogenital distance may contribute to the development of the rectal prolapse in FREM1-deficient mice." (PMID 23536828, 2013).
Upper eyelid coloboma (1 paper, 2023). A short discontinuity of the margin of the upper eyelid. "Thus, we suggest that the FREM1 gene on chromosome 12 could also be associated with upper eyelid coloboma." (PMID 38066959, 2023).
cancer (12 papers, 2016 to 2025). A tumor composed of atypical neoplastic, often pleomorphic cells that invade other tissues. "The results demonstrated that FREM1 was predominantly expressed in cancer-associated fibroblasts (CAFs), with minimal expression in other cell types." (PMID 41324818, 2025). "FREM1 in particular functions as a tumor suppressor by inhibiting cancer cell proliferation, migration, and invasion, highlighting its potential for therapeutic exploitation." (PMID 41324818, 2025). "This study identified PSCA as a risk gene (hazard ratio > 1) for BRCA, while FREM1, NPY1R, CCL19 and CLIC6 were the protective genes for the cancer (hazard ratio < 1)." (PMID 39119106, 2024). "To investigate the role of FREM1 gene expression in cancer, we determined the FREM1 mRNA levels in tumor and normal adjacent tissues of 20 cancer types." (PMID 33031059, 2020). "In most types of cancer, FREM1 expression is significantly lower (P value < 0.001) than in adjacent normal tissues." (PMID 33031059, 2020). "TILRR, or FREM1 isoform 2, shows convincing cancer specificity with strong usage and a significantly low hazard ratio (HR)." (PMID 33031059, 2020). "We identified other genes (SLC22A24, SLC25A29 and FREM1) as associated with EMT; they were linked to cancer for the first time." (PMID 27549611, 2016). "Furthermore, cancers with high expression of the FREM1 gene were sensitive to XAV939 and dasatinib and resistant to SB590885 and gemcitabine, and cancers with high expression of ZMYND10 were resistant to XAV939, gemcitabine, and SB590885." (PMID 36158689, 2022). "However, other genes of the same gene family as FREM2, namely FRAS1 and FREM1, were recently reported as cancer-related genes." (PMID 34439271, 2021). "Moreover, the results from 113 paired cancer samples and adjacent tissues demonstrated that FREM1 mRNA level was dramatically downregulated in tumor tissues than in para‐cancerous tissues (p < 0.0001)." (PMID 33058542, 2020). "In spite of these, it remains unknown whether FREM1 is involved in the progression of cancers and whether its expression in BC is related to clinical outcomes and immune infiltration." (PMID 33058542, 2020). "Accordingly, we speculated that the mechanism of FREM1 involving in cancer metabolism may partially be ascribed to the CSPG domain." (PMID 33058542, 2020). "First, we examined the correlation between FREM1 expression and the prognosis of cancer patients." (PMID 33031059, 2020). "We further investigated how SCNA influences gene expression and found the expression of FCN3, FREM1, MNS1, and SMOC2 was significantly positively associated with SCNA in most cancers, which indicated that aberrant SCNA of a gene might contribute to the progression of various cancers." (PMID 40297163, 2025). "Moreover, FREM1 levels increased in the primary tumor and higher cancer stages." (PMID 35909471, 2022). "However, the function of FREM1 in cancer is not well understood." (PMID 35909471, 2022). "The results of GSEA demonstrated that the pathways enriched in the low‐FREM1 expression group are related to cell metabolism, protein synthesis and folding, and cancer‐related signaling, therefore, deletion of this gene might result in a broad alterations of tumor cell biological behaviors." (PMID 33058542, 2020). "The role of the FREM1 (FRAS1‐Related Extracellular Matrix 1) gene in carcinoma has not studied, moreover, the underlying mechanism remains largely unknown." (PMID 33058542, 2020). "Our study explored the relationship between FRAS1, FREM1 and FREM2 promoter methylation and cancer for the first time." (PMID 36249757, 2022). "The mRNA expression levels of FRAS1, FREM1 and FREM2 were analyzed in Oncomine over a cancer-wide range." (PMID 36249757, 2022).
cancer (continued). "Similarly, GSEA of low‐FREM1 expression group based on Hallmarks data set confirmed eight activated pathways involving cell metabolism (glycolysis, oxidative phosphorylation), cell‐cycle regulation (DNA repair, G2M checkpoint), and cancer‐related signaling (Myc‐targets, mTOR signaling, E2F targets)." (PMID 33058542, 2020). "To explore whether FRAS1, FREM1 and FREM2 were involved in the process of immune infiltration in KIRC, we employed TIMER 2.0 to exhibit the landscape of FRAS1/FREM correlating with tumor purity and various immune infiltrates in human cancers." (PMID 36249757, 2022). "Nevertheless, no study on the involvement of FREM1 in carcinoma has been reported." (PMID 33058542, 2020).
tumor (10 papers, 2020 to 2025). "Our findings reveal the vital role of FREM1 in BC, provide an underlying association of FREM1 with tumor–immune interactions, as well as illustrate a potential mechanism for it." (PMID 33058542, 2020). "These associations suggest that FREM1 may influence not only the intrinsic behavior of tumor cells but also the surrounding immune landscape, thereby contributing to the shaping of a more immunologically active tumor microenvironment." (PMID 41324818, 2025). "The novel tuft cell ligands encoded by Frem1, Fras1 and Agt may have tumor suppressor functions, but have also been found to correlate with immune infiltration and metastasis, while Mif could suppress anti-tumor immunity of infiltrating immune cells." (PMID 37386128, 2023). "Differential expression analysis between tumor and adjacent normal tissues revealed that FREM1 showed the most significant downregulation among all candidate genes (p < 0.05), with a consistent protective pattern." (PMID 41324818, 2025). "Given its strongest prognostic performance, most remarkable tumor-specific expression pattern, and putative tumor-suppressive role, we prioritized FREM1 as our primary target for mechanistic investigation." (PMID 41324818, 2025). "Functional validation identified FREM1 as a potential tumor suppressor, providing mechanistic insights into basement membrane biology." (PMID 41324818, 2025). "FREM1 has been identified as a tumor-suppressor, whose downregulation enabled metabolic shift and tumor infiltration, a finding underlined by the monotonic downregulation seen here." (PMID 41048341, 2025). "The low expression level of FREM1 gene was significantly correlated with advanced clinical stage (p = 4.1E-65), high pathological grade (p = 4.6E-66) and tumor metastasis status (p = 0.00066)." (PMID 36249757, 2022). "FREM1 expression in tumor tissues was 1.25-fold (GEO) and 4.18-fold (TCGA) lower than in normal adjacent tissues." (PMID 33031059, 2020). "The low heterogeneity in tumor tissue correlated with high expression of FREM1 in all but one subtype, which is consistent with the positive association between TILRR expression and level of immune cell infiltration." (PMID 33031059, 2020). "The results of CIBERSORT demonstrated that a considerable portion of the immune cells presents pronounced difference between the high‐FREM1 and low‐FREM1 expression groups, undoubtedly indicating a key regulator of FREM1 in tumor immune microenvironment." (PMID 33058542, 2020). "As possible mechanisms, reduced FREM1 expression was related to tumor cell metabolism and protein synthesis process, while increased FREM1 expression was associated with high‐level infiltration of antitumor immune cells in BC." (PMID 33058542, 2020). "In the present study, we found that FREM1 expression was significantly decreased in BC tissues compared with that in adjacent non‐tumor tissues by bioinformatics and IHC." (PMID 33058542, 2020). "In the validation cohort from GSE53757, TNFSF13B, CASP5, and GJB6 correlated positively with tumor stages, while FREM1 negatively correlated with tumor stages." (PMID 32311223, 2020). "Conversely, FREM1 expression showed an inverse relationship with ​​immunosuppressive cell populations, particularly regulatory T cells (Tregs)​​, which are known to inhibit effective immune surveillance and promote tumor immune evasion." (PMID 41324818, 2025). "Finally, using single-cell RNA sequencing data from two independent datasets-GSE148673 and GSE176078 -we performed a comprehensive analysis of FREM1 expression across diverse cell populations within the tumor microenvironment." (PMID 41324818, 2025). "In contrast, FREM1 expression appeared to be negatively correlated with immunosuppressive cell populations such as regulatory T cells (Tregs), which are known to dampen anti-tumor immune responses." (PMID 41324818, 2025).
tumor (continued). "This fibroblast-specific expression pattern suggests that FREM1 may play a crucial role in tumor-stroma interactions and extracellular matrix remodeling." (PMID 41324818, 2025). "We analyzed the gene expression levels of 12 hub genes with clinical tumor stages and found that TNFSF13B, CASP5 and GJB6 correlated positively with tumor stages, while FREM1 showed negative associations with tumor stages." (PMID 32311223, 2020). "We therefore asked whether or to what extent FREM1 expression alters the distribution of immune cells within the local tumor microenvironment of BC." (PMID 33058542, 2020). "In tumor biopsy samples, FREM1 expression was reduced by as much as 6.16-fold (P < 0.001)." (PMID 33031059, 2020). "Genes specifically lost in tumour samples with high NCS include KIAA1644, TAMM41, GRM7, TTC39B and FREM1." (PMID 35326573, 2022). "The expression levels of FRAS1, FREM1 and FREM2 in both KIRC and non-tumor tissues were also measured by qRT-PCR verification, which confirmed the expression profiles of FRAS1/FREM family." (PMID 36249757, 2022). "Therefore, we speculated that FREM1 may interact with other chemokines or cytokines existing in the tumor microenvironment through this domain, thereby playing a role in recruiting antitumor immune cells homing to the tumor locality." (PMID 33058542, 2020). "Together, these findings highlight FREM1's unique role in shaping the tumor microenvironment-not only through its involvement in stromal and matrix-related processes but also potentially through its influence on immune cell composition." (PMID 41324818, 2025). "Besides, FRAS1, FREM1 and FREM2 mRNA and protein expressions were correlated with the clinicopathological characteristics (pathological stage, grade and tumor metastasis status) of the patients with KIRC." (PMID 36249757, 2022). "The FREM1 commercial polyclonal antibody blotting pattern was identical to that of the TILRR polyclonal antibody, which detected a 75 KDa peptide with an approximately 4.76- and 9.09-fold reduction in expression in tumor tissues." (PMID 33031059, 2020). "A possible explanation for the alteration of immune cells distribution affected by FREM1 could be attributed to the C‐type lectin‐like domain in the C‐terminus of FREM1 protein structure, which is regarded as an immune‐regulatory receptor involving nonspecific and specific tumor immune responses." (PMID 33058542, 2020).
kidney disorder (2 papers, 2016 to 2025). A disease involving the kidney. "The identification of two novel FREM1 variants suggests a previously unreported genetic contribution to syndromic renal diseases in our cohort." (PMID 41288877, 2025).
FREM1 also shares sentences with these, for which no sentence is quoted: infection (8 papers); bifid nose (2); anal stenosis (1); Anophthalmia (1); Apert syndrome (1); atherosclerosis (1); clear cell renal cell carcinoma (1); cleft palate (1); Crouzon syndrome (1); diabetes (1); eyelid coloboma (1); Genital ulcers (1); imperforate anus (1); legionellosis (1); lung fibrosis (1); malaria (1); mastitis (1); mental retardation (1); metopic craniosynostosis (1); nicotine addiction (1); Obesity (1); orofacial clefting (1); ovarian carcinoma (1); pancreatic cancer (1); Pfeiffer syndrome type 1 (1); rectal tumor (1); Salmonella Infections (1); stenosis (1); syndactyly (1); trigonocephaly type 2 (1).
A further 2 diseases each share a sentence with FREM1 in 1 paper.